TRPM8 (transient receptor potential cation channel subfamily M member 8)
Diseases named in the same sentence as TRPM8 in open-access papers (continued):
Sharing a sentence is not in itself a finding about the gene and the disease.
prostate carcinoma (continued). "Initially isolated from prostate cancer cells, TRPM8 channels are mainly expressed in a subpopulation of sensitive primary afferent neurons, which innervate highly cold-sensitive tissues, including skin, the oral cavity epithelium, teeth, nasal mucosa, tongue, and cornea." (PMID 34445208, 2021). "Moreover, testosterone (10 μM) facilitates the migration of prostate cancer cells by inhibiting TRPM8 channels." (PMID 32210800, 2020). "In addition, internalization of normal plasma membrane TRPM8 was observed in the prostate tumor, and internalization and subsequent degradation of cancer cells were correlated with the severity of prostate cancer." (PMID 32168794, 2020). "Moreover, TRPM8 channels are down-regulated as prostate cancer cells turn into androgen-independent cells." (PMID 32210800, 2020). "Additionally, TRPM8 reduces RACK1-mediated ubiquitination of HIF-1α to elevate HIF-1α expression during the hypoxic growth adaptation of prostate cancer cells." (PMID 33344232, 2020). "For example, TRPM8 overexpression induces resistance to paclitaxel in prostate cancer cells." (PMID 32575381, 2020). "Moreover, TRPM8 is critically involved in prostate cancer not only because it is highly expressed in prostate epithelium and prostate cancer cells, but also the hormone testosterone works as an endogenous ligand to bind and activate this channel." (PMID 32728032, 2020). "Moreover, the direct relationship between the TRPM8 channel and androgens was determined in prostate cancer biopsies from patients that received anti-androgenic therapy; in these samples TRPM8 gene expression was downregulated." (PMID 32471309, 2020). "Likewise, testosterone activates TRPM8 through a direct interaction of the steroid with the channel, modifying migration in human prostate cancer cell lines and the cold perception in mammals." (PMID 32471309, 2020). "In addition, an increase of [Ca2+]i concentration through menthol activation of TRPM8 channels in the prostate cancer cells induced increase the rate of mitochondrial oxidative stress, resulting apoptosis of the cancer cells." (PMID 30858386, 2019). "Thus, the pro-apoptotic effects of oxidative stress in the cancer cells, including prostate cancer cells seem to be dependent on one single mechanism, e.g., the ability of TRPM8 activation to generate oxidative stress." (PMID 30858386, 2019). "Activation of TRPM8 channel through oxidative stress may induce Ca2+ and pro-apoptotic signals in prostate cancer and kidney cells." (PMID 30858386, 2019). "However, it was recently shown that the migration of prostate cancer cells was inhibited when TRPM8 was activated by icilin and menthol." (PMID 31138874, 2019). "Interestingly, the encapsulated WS12 potentiated TRPM8-mediated prostate cancer cell migration in transwell assays as well as in the zebrafish model." (PMID 31138874, 2019). "Next, we examined whether TRPM8 were attenuated in ROS-induced apoptosis, cell viability and caspase activation by determining the effects of ACA as a TRPM8 inhibitor, on oxidative stress-induced prostate cancer cell apoptosis and generation of ROS." (PMID 30858386, 2019). "However, it has been shown that in prostate cancer cells, TRPM8 is also detected in endoplasmic reticulum membrane and MAM." (PMID 29875336, 2018). "Indeed, the level of TRPM8 expression in normal prostate cells is very low, while in prostate cancer cells, it increases drastically." (PMID 29875336, 2018). "Together, our results indicate that enhanced TRPM8 hydrolysis in prostate cancer could present an adaptation mechanism, sustained via bypassing testosterone-induced rapid Ca2+ uptake through TRPM8, thus, diminishing the rates of apoptosis." (PMID 28039451, 2017). "Considering that TRPM8 might play a similar protective role in the human prostate, here we investigated the TRPM8 expression pattern in the tissues from the prostate cancer patients." (PMID 28039451, 2017).
prostate carcinoma (continued). "Furthermore, the TRPM8 protein degradation was also evident in the tissues of PC patients, confirming that it is a characteristic phenomenon common to prostate cancer progression." (PMID 28039451, 2017). "Establishing the precise mechanism of TRPM8 protein hydrolysis and identifying the routes for its recovery in PC cells may enable novel and specific tools to fight prostate cancer." (PMID 28039451, 2017). "Consequently, TRPM8 has been suggested as an important ER Ca2+ release channel, which is involved in numerous processes in prostate cancer epithelial cells." (PMID 28861042, 2017). "Taken together, these results reinforce the hypothesis that TRPM8 could play a protective role in prostate cancer progression by reducing both cell migration and angiogenesis." (PMID 27409624, 2016). "Indeed, we as well as others suggest a putative protective role for TRPM8 in prostate metastatic cancer progression, since enhancement in channel expression and/or an activation, blocks prostate cancer cell migration." (PMID 27409624, 2016). "Indeed, mice transplanted with prostate cancer cells over-expressing TRPM8 develop tumors that are less vascularized than control cases." (PMID 27409624, 2016). "Since sM8s are negative regulatory sub-units of the cold and menthol receptor, and because TRPM8 channel has been considered as a target of interest in cancer therapy, we assessed whether sM8s knockdown (KD) could affect prostate cancer cell growth." (PMID 27074561, 2016). "However, findings from the expression analyses suggest that TRPM8 channels play a regulatory role in prostate cancer growth and metastasis." (PMID 26512697, 2015). "TRPM8 channels endogenously expressed in the prostate cancer cell line LNCaP display strongly divergent biophysical properties compared to TRPM8 channels in DRG cells (e.g. they have an inward rectifying I/V relationship) but also appear to be permeable to Ca2+, Sr2+, Ba2+ and Mn2+." (PMID 25106481, 2015). "The cold and menthol receptor TRPM8 is highly expressed in prostate and prostate cancer (PC)." (PMID 25980497, 2015). "Moreover, TRPM8 is overexpressed in different carcinomas and has been proposed to be a “prooncogenic receptor” in prostate cancer cells." (PMID 25710007, 2015). "Besides prostate carcinoma, the expression levels of TRPM8 were significantly higher in urothelial carcinoma of bladder tissues than in non-cancerous urothelial tissues." (PMID 26512697, 2015). "Recent evidence indicates that TRPM8 protein undergoes ubiquitin-mediated degradation in prostate cancer cells, and the TRPM8 channel activity on the plasma membrane could be increased by inhibiting the initial enzyme in ubiquitination." (PMID 26512697, 2015). "In particular, Nilius and co-workers suggest that menthol (TRPM8 agonist) accelerates cell migration of glioblastoma cells; on the other hand, pharmacological agents inhibiting TRPM8 reduce cell speed of prostate cancer cells." (PMID 24204345, 2013). "Taken together these three studies suggest that TRPM8 could play a protective role in prostate cancer progression by reducing both cell migration and angiogenesis." (PMID 24204345, 2013). "Our main goal was to test whether TRPM8 activity is a general requirement for the proliferation of different prostate cancer cell lines." (PMID 23251635, 2012). "TRPM8 channels have been attributed a role in the generation and progression of prostate cancer." (PMID 23251635, 2012). "Inhibitors of TRPM8 reduce the growth of prostate cancer cells." (PMID 23251635, 2012). "Overexpression of the cation-permeable channel TRPM8 in prostate cancers might represent a novel opportunity for their treatment." (PMID 23251635, 2012). "Also, TRPM8 was suggested to act as a “Ca2+ release channel” on stores in prostate carcinoma cell lines." (PMID 20674014, 2010).
prostate carcinoma (continued). "Indeed, the androgen regulation of TRPM8 expression was reported in prostate cancer and putative androgen receptor response elements were identified in the TRPM8 gene." (PMID 20482834, 2010). "In addition, testosterone was shown to increase intracellular Ca2+ influx and activate the TRPM8 channel in PC-3 prostate cancer cells, dorsal root ganglion and hippocampal neurons, and the human embryonic kidney cell line HEK293 with almost the same affinity and specificity as for the nAR." (PMID 36835177, 2023). "Additionally, TRPM8 is also expressed in prostate cancer cells." (PMID 36555804, 2022). "The physiological role of TRPM8 regulation by androgens in prostate cancer cells has been linked to cell proliferation since the overexpression or activation of this channel in the PC3 cell line has an anti-proliferative effect, supporting the anti-tumorigenic role of TRPM8 channels." (PMID 32471309, 2020). "Interestingly, several groups have reported the role of TRPM8 in prostate cancer progression." (PMID 33291725, 2020). "Hence, activation of TRPM8 through oxidative stress may induce pro-apoptotic signals in prostate cancer cells, but it remains unclear." (PMID 30858386, 2019). "However, the ultimate question remained whether TRPM8 degradation also takes place in prostate cancer patients, and if so can its recovery be used as a tool to control the tumor growth." (PMID 28039451, 2017). "However, the results till now support the hypothesis that TRPM8 increase in the first androgen-dependent stages of PCa has a protective role regarding the invasive character of prostate cancer cells." (PMID 27409624, 2016). "Similarly, in the TRPM and TRPV family, TRPM8 and TRPV6 are considered oncogenes and their upregulated expression in prostate cancer may constitute new diagnostic markers for that disease." (PMID 22523714, 2012). "Therefore, TRPM8 channels can be considered as a valuable prognostic marker in prostate cancer." (PMID 20482834, 2010). "In prostate cancer cells, activation of the TLR3-NF-κB/IRF signaling cascade by TRPM8 triggers a sterile inflammatory response." (PMID 41601666, 2026). "The research investigates how the encapsulated WS12 affects the migration of prostate cancer cells mediated by TRPM8 both in vivo and in vitro, and demonstrates WS12’s affinity and specificity for TRPM8 by making it a successful channel agonist." (PMID 40922741, 2025). "TRPM8 activation by agonist WS12, when loaded with LNC, greatly inhibited the migration of Prostate Cancer cells." (PMID 40922741, 2025). "TRPM8 activator D3263, a clinical Phase 1 dose escalation study (NCT00839631), helped patients with prostate cancer stabilize their condition." (PMID 40813985, 2025). "Prior research on prostate cancer has unearthed parallel findings, where TCAF2’s interaction with TRPM8 facilitates its cell surface transport and suppresses its ion channel activity, effectively enhancing the migration of prostate cancer cells in vitro." (PMID 39062591, 2024). "The recruitment of TRPM8 to the cellular membrane and the facilitation of migration in prostate cancer cells is attributed to the actions of TCAF2, which operates in a TRPM8-dependent manner." (PMID 38019450, 2024). "The analysis of protein interactions demonstrated that TRPM8 channels are physically connected with TCAF2, which has an inhibitory role on channel activity, promoting prostate cancer cell migration." (PMID 37033630, 2023). "As in humans, the mouse prostate expresses a higher amount of Trpm8 than other murine tissues, comparable to the levels of the channel found in normal prostate immortalized (RWPE-1 and PWR-1E) and prostate cancer human-cell lines (LNCaP, VCaP, C4-2)." (PMID 35204694, 2022). "In prostate cancer, TCAF1 negatively regulates cell migration when bound to TRPM8, but TCAFs are partner proteins for other ion channels, including TRPV6." (PMID 36012311, 2022).
prostate carcinoma (continued). "TRPM8 is the most studied TRP channel, because, out of all the family members, it has the highest levels of expression in different cancer types such as prostate cancer, colon cancer, breast cancer, melanoma, and PDAC." (PMID 36012311, 2022). "All these results suggest TRPM8 and TRPV6 channels as potential markers for prostate cancer progression and prognosis." (PMID 32210800, 2020). "TRPM8′s activation by testosterone has also been observed in DRG and hippocampal neurons and in PC3 cells (a prostate cancer cell line which lacks AR expression)." (PMID 32471309, 2020). "As expected, KLK3 Ct values strongly correlated with Ct values of other genes which have been reported to play a role in prostate cancer (i.e., PCA3, AMACR, TRPM8, MSMB and PSGR)." (PMID 32630458, 2020). "For the TRPM8 activator D3263, a clinical Phase 1 dose escalation study (NCT00839631) led to disease stabilization in prostate cancer patients." (PMID 29772843, 2018). "In addition, TRPM8 is highly upregulated in an early, differentiated stage but downregulated during malignant progression of prostate cancer which might suggest that TRPM8 is involved in early prostate carcinogenesis but rather suppresses than promotes malignant progression." (PMID 29221175, 2017). "Other TRP subfamilies have also been demonstrated in the cancer development, such as TRPM1 in melanoma, TRPM7 in human retinoblastoma cells and human head and neck carcinoma cells, TRPM8 and TRPV6 in prostate cancer." (PMID 23840757, 2013). "TRPM1, TRPM8, and TRPV6 are considered to be tumor suppressors and oncogenes in localized melanoma and prostate cancer, respectively." (PMID 22523714, 2012). "In addition, the authors have found that TRPM8 and TCAF1 are upregulated in primary prostate cancer samples and downregulated in metastatic samples." (PMID 38816425, 2024). "Indeed, TRPM8 expression was shown to increase in both benign prostate hyperplasia (BPH) and in prostate carcinoma cells characterized by high androgen levels but decrease with tumor progression to the late androgen-insensitive invasive stage." (PMID 35565390, 2022). "However, most lines of evidence, including the present study, strongly suggest an anti–migratory role of TRPM8, shedding light on the possibility of using TRPM8 agonists, such as PSA, WS12, and icilin, to counteract the metastasis of prostate cancer." (PMID 35743115, 2022). "Conversely, TRPM8 wt decreases cell migration in MCF-7 cells, while TRPM8 E207A Y240A does not (Figure 8bii), thus suggesting the involvement of the TRPM8-Rap1 interaction in the control of the migratory phenotype of breast cancer similarly to prostate cancer." (PMID 35565390, 2022). "Although prostate cancer cells depend on the Ca2+ infiltration of TRPM8 for invasion and metastasis, non-physiological activation of TRPM8 by menthol inhibits the proliferation and motility of CRPC." (PMID 36389722, 2022). "We demonstrate that Trpm8 expression is enriched in mouse prostate luminal cells, and, as in humans, it marks hormone naïve prostate cancer cells independent of the genetic and molecular drivers that promote tumorigenesis." (PMID 35204694, 2022). "In recent years TRPM8 (transient receptor potential cation channel subfamily M member 8) and GPRC6A (G protein-coupled receptor class C group 6 member A) proteins were demonstrated to mediate the action of androgens in prostate cancer cells." (PMID 33167316, 2020). "Indeed, the classical TRPM8 agonist menthol has been shown to inhibit cell proliferation, induce cell cycle arrest, and inhibit migration of the androgen-independent DU145 prostate cancer cell line." (PMID 32825277, 2020). "TRPM8 is expressed in prostate cancer with negative correlation to tumor severity: as the cancer progresses, its TRPM8 expression decreases." (PMID 32887395, 2020). "Activation of TRPM8 through oxidative stress and ADPR in the cells could be used as an effective strategy in the treatment of prostate cancer cells." (PMID 30858386, 2019).
prostate carcinoma (continued). "Overall, these results demonstrate that encapsulating WS12 into LNC600 potentiated the effect of WS12 on TRPM8 activation regarding prostate cancer cell migration and was not toxic in vivo." (PMID 31138874, 2019). "The aim of this study was to evaluate activation of TRPM8 can increase apoptosis and oxidative stress in the prostate cancer (Du145M8), TRPM8 knock out (Du 145M8KO), transfected (HEK293TM8) and non-transfected human kidney (HEK293) cells." (PMID 30858386, 2019). "At the same time, in non-prostate-cancer model cell culture, PSA was able to potentiate the TRPM8 agonist-induced calcium current by enhancing trafficking of the channel to the plasma membrane via its phosphorylation downstream of the bradykinin 2 receptor signaling pathway." (PMID 29671777, 2018). "Although TRPM8 mRNA levels increase at the early prostate cancer stages, we found that it is not proportionally translated into TRPM8 protein levels." (PMID 28039451, 2017). "On the other hand, testing the TRPM8 expression profile and responsiveness to its agonists in LNCaP cells indicated the lack of the channel expression on the plasma membrane of prostate cancer cells." (PMID 28039451, 2017). "In AR- prostate cancer PC-3 cells that do not express TRPM8, ectopic expression of TRPM8 showed inhibitory effect on cellular proliferation." (PMID 26512697, 2015). "In AR− prostatic carcinoma and the lung cancer cell line, TRPM8 channels play a negative role in cellular proliferation." (PMID 26512697, 2015). "As nonspecific bands were detected, LNCaP prostate cancer cell line was used as TRPM8-positive control to assess the right band size, and β-actin was used as loading control." (PMID 24593692, 2014). "Again, these results indicate that although TRPM8 is important to sustain proliferation and migration of prostate cancer cells (but not of normal epithelium), it is not the only determinant of this process." (PMID 23251635, 2012). "We set to determine expression levels of TRPM8 in the prostate cancer cells LNCaP, PC3 and DU145 and the non-tumoral cell line PNT1A by different approaches to expand and complement results reported before." (PMID 23251635, 2012). "In summary, we provide evidence supporting a tumor-specific role of TRPM8 rather than a tumor-specific expression of the channel, thus reinforcing the relevance of this channel as a promising candidate for prostate cancer therapy." (PMID 23251635, 2012). "In addition, TRPM8 (melastatin-related TRP member 8) channel is found to be over-expressed in several primary tumours including colon, lung, skin, and prostate cancer." (PMID 20482834, 2010). "Indeed, the expression of TRPM8 in neuronal and non-neuronal cells is relevant for cold hypersensitivity, nerve injury, chronic pain, and also in prostate cancer." (PMID 39150496, 2024). "TRPM8, as a member of the transient potential receptor family, has been shown to be highly expressed in androgen-sensitive cancer cells, is a potential prognostic marker for metastatic CRPC, and is also considered a promising druggability target for the treatment of prostate cancer." (PMID 36389722, 2022). "However, there is no report ADPR and H2O2 dependent activation of TRPM8 in the prostate cancer and human embryonic kidney cells 293 (HEK293) cells." (PMID 30858386, 2019). "Recent evidence suggests that the prostate cancer (PCa)-specific up-regulation of certain genes such as AMACR, EZH2, PSGR, PSMA and TRPM8 could be associated with an aberrant expression of non-coding microRNAs (miRNA)." (PMID 24517338, 2014). "Interestingly, the well-known prostate cancer marker, Prostate Specific Antigen (PSA) that is secreted in the prostatic acini and is therefore in contact with the extracellular part of TRPM8, activates the channel and decelerates cell migration by inducing its plasma membrane accumulation." (PMID 24204345, 2013).